STAT3 (signal transducer and activator of transcription 3)
Diseases named in the same sentence as STAT3 in open-access papers (continued):
Sharing a sentence is not in itself a finding about the gene and the disease.
tumor (continued). "For instance, aberrant IL-6/JAK/STAT-3 signaling potentiates inflammatory responses in COVID-19, therefore aggravating disease severity; in the context of cancer, it attenuates anti-tumor T-cell mediated responses and favors tumor growth, survival, invasiveness, and or/metastasis." (PMID 36298472, 2022). "Due to its central role in tumor processes, STAT3 has been considered a potential anticancer target since its first description as an oncogene in 1998 and has led to the evaluation of STAT3 inhibitors for their antitumor activity in vitro and in vivo using experimental tumor models." (PMID 35886918, 2022). "Therefore, STAT3 is considered as a tumor progression factor in TNBC." (PMID 35314590, 2022). "In addition, STAT3 becomes phosphorylated (hyperactivated) not only in the tumour cells but also in immune cells and CAFs within the TME, which could impact anti-tumor immunity." (PMID 35844493, 2022). "This work also highlights a theoretical limitation of anti-tumor immunity, as even in a model system where all the ‘breaks’ on T cell activity are removed, tumor cells may activate a STAT3 transcriptional program, which promotes spatial architecture impenetrable to cytotoxic mediators." (PMID 36124553, 2022). "In many cancer types, STAT3 does not directly rely on its activation by oncogenic mutations but has important oncogenic and malignant transformation-associated functions in both cancer and stromal cells in the tumor microenvironment (TME)." (PMID 36010693, 2022). "IL-11 could promote STAT3 activation and inflammatory cancer progression in an autocrine manner, and Serpin E2 could promote the progression of invasion and metastasis by reprogramming the tumor vascular system." (PMID 35382893, 2022). "The STAT3-dependent tumor-associates factors such as IL-10, VEGF and basic fibroblast growth factor (bFGF) could strengthen the immunosuppressive network and promote tumor vasculariztion that hinders IFN-γ-dependent effect of CD8+ T cells." (PMID 34875483, 2022). "Given the broad activities of Stat3 as an enabler of cancer-cell-extrinsic hallmark capabilities, it will be important to establish the extent to which they also depend on miR-21 induction in the non-neoplastic cells of the tumor microenvironment." (PMID 35053428, 2022). "Interestingly, in the tumor microenvironment surrounding tumor cells, IL-6 is also produced by other kinds of cells, such as tumor-infiltrating immune cells and stromal cells, resulting in the hyperactivation of STAT3 signaling." (PMID 35956786, 2022). "Interferon-γ induces CD8+ T cells to antigen (Ag)-specific CTLs and CD4+ T cell differentiation, however, continuous exposure to interferon-γ may induce T cell exhaustion and tumor progression by inducing immune escape mediators, including PD-L1, STAT3, and IDO1." (PMID 36006412, 2022). "Indeed, in vivo studies have suggested that this may represent a tumor suppressor role, with RUNX1 able to directly repress Socs4 expression leading to increased STAT3 activity, which contributes to tumor development." (PMID 35204004, 2022). "In addition, YTHDF2 could inhibit the phosphorylation of STAT3 and the expression of Serpin E2, thereby reducing tumor growth and angiogenesis and resisting the occurrence of inflammatory cancer progression." (PMID 35382893, 2022). "STAT3 plays a key role in normal cell growth, such as embryogenesis, and is constitutively activated in approximately 70% of solid and hematological cancers in human medicine, and is involved in cell proliferation, survival, angiogenesis, and tumor-mediated immune evasion." (PMID 35836213, 2022). "Thus, inhibiting STAT3 activity in tumor cells could reduce immunosuppression in the TME and enhance the effector function of CD8+ T cells." (PMID 34875483, 2022).
tumor (continued). "Furthermore, although Stat3 phosphorylation of Tyr705 and Ser727 was associated with less aggressive tumor characteristics such as tumor size or clinical stage, neither phosphorylation showed an association with survival." (PMID 36017196, 2022). "However, STAT3 also paves the way for tumour growth through immunosuppression." (PMID 35665592, 2022). "Our observation that STAT1 and STAT3 expression exhibit strong positive correlation in the tumor cells and the immune cell infiltrate suggest that both may similarly indicate the state of the tumor microenvironment." (PMID 35267462, 2022). "This SIRT interacts directly with signal transducer and activator of transcription 3 (STAT3) regulating its phosphorylation and its translocation in the nucleus, thus causing an increase in vascular endothelial growth factor A (VEGFA) secretion furthering angiogenesis, tumor survival and growth." (PMID 35328633, 2022). "In addition, STAT3 phosphorylation in the tumor tissues was heightened by RFX3-AS1 overexpression." (PMID 35475457, 2022). "Sequential intravenous injections of STAT3 siRNA resulted in profound suppression of STAT3 expression in tumor tissue, resulting in considerable downregulation of programmed death ligand‐1 (PD-L1) and significant tumor growth inhibition via inactivation of the tumor immune checkpoint." (PMID 36476230, 2022). "Aberrantly-active Stat3 promotes tumor progression in part through its direct dysregulation of gene expression and cross-talks with other key proteins, including nuclear factor (NF)-κB, leading to uncontrolled growth and survival of tumor cells, enhanced tumor angiogenesis, and tumor metastasis." (PMID 35276290, 2022). "Although predictions made from these experiments are consistent with in vivo studies of combinations of ispinesib and saracatinib in murine GBM models, it remains possible that local variations in microenvironment from tumor to tumor may alter the efficacy of combined Kif11 and STAT3 targeting." (PMID 35732128, 2022). "Interestingly, STAT1 and STAT3 exhibited highly positive correlations in the tumor epithelium." (PMID 35267462, 2022). "Specifically, STAT3 was found to be crucial for tumor progression through different mechanisms that include direct effects on proliferation, angiogenesis, apoptosis, and survival, as well as having a non-direct effect on the immune and stromal environment surrounding the tumor." (PMID 35327992, 2022). "Therefore, activated STAT1 and activated STAT3 signaling in the tumor cells was observed in a subsets of HCC patients and may indicate a specific HCC subgroup with high immune cell infiltration." (PMID 35267462, 2022). "Notably, GSEA analysis also indicated upregulation of epithelial-mesenchymal transition (EMT), inflammatory response, and interleukin-6 (IL-6)-STAT3 signaling in bulk RNA-seq data, which concurs with the observed invasive tumor phenotypes and proposed iCAF switching in the PKN2KO cohort." (PMID 35081338, 2022). "In addition, PA28γ stimulated OSCC tumor angiogenesis in an IL-6/CCL2/STAT3 axis-dependent manner." (PMID 36231093, 2022). "Furthermore, STAT3 is involved in tumor-related immunosuppression at many levels." (PMID 35936759, 2022). "Additionally, IL-6 secreted by MSCs could also signal through STAT3 to increase the number of colorectal initiating tumor cells and promote tumor formation." (PMID 35281017, 2022). "In addition, lncRNA-NEAT1 directly targets the expression of many prometastatic genes and tumor microenvironment-related genes (such as STAT3, WNT7A and VEGF-A) by interacting with miR-361, while miR-361 can inhibit tumor proliferation, invasion, stemness and paclitaxel resistance." (PMID 36601121, 2022).
tumor (continued). "Furthermore, research has also discovered an intermediate state between the iCAF and myCAF phenotypes termed α-SMA + p-STAT3 + cells, which might subsequently be a potential target for tumor immunotherapies." (PMID 34635121, 2021). "In ovarian cancer, the previous studies showed that ROS could activate various oncogenic transcription factors such as NF-κB, AP-1, and STAT3, to influence cellular transformation, tumor cell proliferation, inflammation, tumor cell survival, metastasis and invasion, and angiogenesis." (PMID 34557266, 2021). "Thus, STAT3 blocking has been proposed to be a promising adjuvant for the tumor immunotherapy." (PMID 33957948, 2021). "ESR1 may exert a tumor suppressor function by inhibiting the JAK/STAT3 pathway." (PMID 33865377, 2021). "We reasoned that since CDK2/4/6 and STAT3 clustering networks were enriched in cancer and inflammatory/immune-related pathways, then their hyper-expression levels in multiple cancers may be correlated with tumor immune infiltration." (PMID 33668805, 2021). "Studies have also found that activation of STAT3 could induce tumor angiogenesis." (PMID 34141710, 2021). "Furthermore, STAT3 regulates immunosuppressive factors from the tumor cells themselves." (PMID 33786638, 2021). "Activated STAT3 helps tumor cells to proliferate, survive insults, resist noxious chemicals and potent inflammatory mediators, and it supports aerobic glycolysis, reduces reactive oxygen species, and protects tumor-initiating cells also known as cancer stem-like cells (CSC)." (PMID 35048056, 2021). "Also, crosstalk between human and murine IL6 pathways in the murine tumor microenvironment by tumor-infiltrating immune cells or fibroblasts can potentially prime the metastatic niche and hyperactivate STAT3 pathways in cancer cells through IL6 trans-signaling pathways." (PMID 34262028, 2021). "Moreover, IL-6, IL-10 and VEGF, produced by cancer cells, may activate STAT3 in a paracrine fashion in the cells present in the tumor microenvironment, such as myeloid cells or fibroblasts, transforming them into cells that support tumor growth." (PMID 33513694, 2021). "Thus, AIM2 in NSCLC exerts tumor‐promoting effects in an inflammasome‐dependent manner and regulation of mitochondrial dynamics, presumably triggering an IL‐1β/STAT3 response by the nuclear factor‐κB (NF‐κB)/COX‐2/HIF‐1α pathway and contributing to the MAPK/ERK pathway activation." (PMID 34014039, 2021). "Thus, STAT3 blockade inhibited both L1CAM-dependent tumor initiation and growth." (PMID 34645505, 2021). "Therefore, our approach was to target two critical proteins, Ref‐1 and STAT3, whereby the propagation of signals between tumour and its microenvironment can potentially be blocked leading to a sensitization of the tumour to chemotherapy leading to a tumour‐induced cell death." (PMID 33274592, 2021). "Indeed, STAT3 plays a key role as a mediator of tumor immune evasion." (PMID 34830179, 2021). "Indeed, combinational therapy using both NF-κB inhibitors and inhibitors of other transcription factors, such as STAT-3, has shown effective antitumor outcomes, as the STAT-3 signaling pathway that fuels tumor promotion and mediates immune escape has important crosstalk with NF-κB." (PMID 34277453, 2021). "Notably, these elevated cancer -promoting inflammatory cytokinesare regulated by STAT3 pathway, indicating that LIN28B possibly promotes malignant cholangiocytes transformation by inducing the expression of tumor -promoting inflammatory cytokines via STAT3 signaling pathway." (PMID 34837926, 2021).
tumor (continued). "In other words, in PTEN-deficient GBM (found in ~35% of GBM), STAT3 may be tumor suppressive rather than oncogenic." (PMID 33498872, 2021). "These cytokines might activate tumor cell proliferation through STAT3 and NF-kappa beta pathways." (PMID 35008550, 2021). "Furthermore, hydrazinocurcumin down-regulated a series of immunosuppression-related proteins and downstream target molecules of STAT3, thereby limiting the proliferation and migration of 4T1 breast cancer cells in vitro, as well as tumor growth, angiogenesis and metastasis in vivo." (PMID 34683963, 2021). "Thus, host-specific genetic variants might dictate immunosuppressive crosstalk between tumor cells and CD8+ T cells through STAT3 pleiotropic functions in T cells." (PMID 33957948, 2021). "The role of STAT3 in mediating immune evasion by OS tumours is largely unknown." (PMID 33382511, 2021). "Overall, the abundance and multiplicity of activators of the STAT3 TF and the diversity of downstream effectors induced following irradiation suggest the idea to target STAT3 as a combined treatment with X-rays to increase the efficiency of tumor eradication in the majority of cancer types." (PMID 34141616, 2021). "Preclinical studies indicate increased IL‐6/JAK/STAT3 signalling in tumour cells and tumour infiltrating immune cells could promote tumour proliferation, survival, invasion and metastasis, and might suppress anti‐tumour immunity." (PMID 33382511, 2021). "Thus, persistently activated STAT3 maintains the constitutive NF-κB activity in tumor cells." (PMID 34443544, 2021). "Likewise, IL-6 and leptin derived from adipocytes could increase the PD-L1/NKG2D ligand level in cancer cells by activating the JAK/STAT3 signaling pathway, thereby decreasing the cytotoxicity of NK cells to tumor cells." (PMID 33413697, 2021). "However, because numerous TKs share a common ability to induce downstream signaling effectors, nintedanib-treated NSCLC cells can engage feedback activation mechanisms such as STAT3, which are capable of promoting cell survival and limiting overall drug response in tumor cells themselves." (PMID 34439322, 2021). "Moreover, the role of STAT3 as a tumor-suppressor is controversial: several studies point to a pro-angiogenic role of STAT3 in several cell contexts; but STAT3 also shows tumor suppressor function in different cancer contexts by activating various molecular mechanisms." (PMID 33578955, 2021). "Finally, our results further show that STAT3 activation was elevated in the immune cells exposed to PARP inhibitor-resistant tumor cells, which was contributed by an increase in IL-6 expression by Olaparib-resistant OVCAR8 cells relative to their parental counterparts." (PMID 34956861, 2021). "Existing therapies under tumor-bearing conditions, such as MDSCs depletion with low-dose chemotherapy or tyrosine kinase inhibitors, MDSCs differentiation using all-trans retinoic acid, and STAT3 inhibition merit clinical evaluation during the perioperative period." (PMID 33258011, 2021). "Furthermore, tumor cell-extrinsic STAT3 activation also regulates the immune tolerance and suppression of anti-tumor immunity by upregulating the expression of immune checkpoint proteins (e.g., PD1, CTLA4) on the surface of tumor-associated myeloid cells, B-cells, Tregs, and CD4 and CD8 T-cells." (PMID 34944848, 2021). "Furthermore, we evaluated the level of STAT3 in tumor specimens by Western blot." (PMID 33995073, 2021). "Notably, tumor-associated macrophage-derived IL-6 binds to receptor/glycoprotein 130 (gp130) and upregulates Janus kinase (JAK)-STAT3 signaling in CRC cells, leading to increased EMT and chemoresistance, which promotes the proliferation and invasion of CRC cells." (PMID 34394377, 2021).
tumor (continued). "Thus, significant enrichment of macrophages M1 activated CD4 memory T cells in the tumor microenvironment and that of the hallmark IL6/JAK/STAT3 signaling pathway in tumor tissues indicate initiation, growth, and escape of OSCC-GB tumor cells from host immune response." (PMID 33980865, 2021). "Thus, hsa_circ_0000117 may function as a tumor promoter during GC progression by regulating the miR-337-3p/STAT3 axis." (PMID 33896365, 2021). "Moreover, GSEA results indicated that the IL6/JAK/STAT3/SIGNALING pathway could be considered as a potential mechanism of genomic instability to influence tumor progression." (PMID 34712264, 2021). "Therefore, inhibiting STAT3 pathways can significantly reduce vascular endothelial growth factors, which could inhibit tumor growth." (PMID 33936081, 2021). "Above all, these data proposed that STAT3 could mediate tumor immunity upon PD-1 blockade." (PMID 33936081, 2021). "Concerning BrCa and PrCa cells, NF-κB and STAT3 are associated with premetastatic niche formation and migration and metastasis to the bone, as well as growth within the bone, at least partially by stimulating RANKL and PTHrP production, thereby accelerating tumor cell-promoted osteoclastogenesis." (PMID 34064859, 2021). "STAT3 is a well-characterized oncogene that affects various biological processes, including promoting cell proliferation and survival by regulating Cyclin D1 and Bcl-2, inducing tumor invasion and metastasis by regulating E-cadherin and MMP-9, and promoting angiogenesis by HIF-1α expression." (PMID 34365889, 2021). "However, mutant STAT3 attenuated the effect of EZH2 knockdown on tumor growth to less extent." (PMID 34335938, 2021). "Constitutively activated STAT3 translocates to the nucleus and enhances gene transcription, which favors cell proliferation, resistance to apoptosis, survival, angiogenesis, tumor-promoting inflammation, tumor-mediated immune evasion, and, ultimately, invasion and metastasis." (PMID 34440220, 2021). "In addition, the JAK/STAT3 pathway may enhance TGF-β-induced epithelial–mesenchymal transition (EMT) to promote tumor metastasis." (PMID 35070978, 2021). "Furthermore, we proposed a mechanism by which tetraarsenic hexoxide induced pyroptotic cell death via mitochondrial ROS-mediated caspase-3/GSDME pathway by inhibiting phosphorylation of mitochondrial STAT3, thereby suppressing tumor growth and metastatic potential of aggressive TNBC cells." (PMID 33558527, 2021). "Similarly, the Aurora A inhibitor alisertib is also reported to disrupt the immunosuppressive functions of MDSCs by inhibiting Stat3-mediated ROS production, which triggers the rapid accrual of cytotoxic T cells, and efficiently inhibits the proliferation of tumor cells." (PMID 35003065, 2021). "Furthermore, STAT3 is always activated and promotes tumor aggressiveness in human HCC." (PMID 34057016, 2021). "Furthermore, some studies also suggest that APN plays a role in regulating tumor cell growth and proliferation and the cell cycle through inhibition of signal transducer and activator of transcription 3 (STAT3), wingless-type protein (Wnt), and ubiquitin-specific protease 2 (USP2)." (PMID 33815885, 2021). "Similarly, STAT3 can also inhibit the expression of miR-218, a tumour suppressor." (PMID 34425834, 2021). "Finally, the role of nSMase2 in the activation of NF-κB induced by PAR4 and the role of NF-κB and STAT3 signaling pathways in the PAR1/PAR4-mediated tumor promoting or suppressive functions were measured by immunoprecipitation, western blot and immunofluorescence assays." (PMID 34844621, 2021). "Therefore, our results suggest that acacetin could be a potent anticancer agent for targeting STAT3-activated tumor cells." (PMID 34684783, 2021). "Furthermore, we performed in-depth studies to understand the mechanism and illustrated that ESR1 may act as a tumor suppressor by inhibiting the JAK/STAT3 signaling pathway." (PMID 33865377, 2021).